NEAT1 (nuclear paraspeckle assembly transcript 1)
Diseases named in the same sentence as NEAT1 in open-access papers (continued):
Sharing a sentence is not in itself a finding about the gene and the disease.
cervical carcinoma (continued). "In this study, we propose that NEAT1 modulates aerobic glycolysis to accelerate cervical cancer progression." (PMID 38733179, 2024). "Downregulation of NEAT1 inhibited the proliferation, migration, invasion and glycolysis of cervical cancer cells, while overexpression of NEAT1 led to the opposite effects." (PMID 38733179, 2024). "Our in vitro study demonstrated that NEAT1 was highly expressed in cervical cancer, promoting the growth, invasion, and migration of cervical cancer cells." (PMID 38733179, 2024). "An experiment reported that NEAT1 expression was increased in cervical cancer tissues and HeLa and SiHa cell lines." (PMID 37310654, 2023). "Through regulation of the miR377/FGFR1 axis, inhibition of NEAT1 decreased cell survival and migration, and accelerated apoptosis in cervical cancer cells." (PMID 37310654, 2023). "In cervical cancer cells, NEAT1 and FGFR1 expression levels were significantly higher, whereas miR-377 expression was significantly reduced." (PMID 37310654, 2023). "This indicates that high expression of NEAT1 is closely related to the resistance of cervical cancer to radiotherapy." (PMID 36890809, 2023). "A recent study detected that NEAT1 functions as an oncogene in patients with cervical cancer and induced worse survival." (PMID 37310654, 2023). "This indicated that high expression of NEAT1 contributes to the resistance of cervical cancer cells to radiation therapy through regulation of the cell cycle and apoptosis." (PMID 36890809, 2023). "It has been shown that PI3K/Akt signaling pathway was well correlated with the regulation of lncRNA NEAT1 in cervical carcinoma proliferation and invasion." (PMID 36644576, 2023). "It has been shown that high expression of NEAT1 increased the proliferation and invasion of cervical cancer cells by targeting cyclin D1, CDK4, AKT/PI3K, and matrix metallopeptidase 2 (MMP2)." (PMID 37310654, 2023). "A recent study revealed that NEAT1 participated in initiation and progression of both cervical cancer tissues and cell lines by binding to miR-9-5p and suppressing its expression." (PMID 37310654, 2023). "It is considered that NEAT1 negatively regulates the expression of miR-193b-3p to affect the radiosensitivity of cervical cancer." (PMID 35692795, 2022). "NEAT1 expression was significantly increased in cervical cancer tissues and radioresistant cervical cancer cells." (PMID 35692795, 2022). "used qRT-PCR to detect the expression of NEAT1 in cervical cancer tissues and radioresistant cervical cancer cells (HeLa-R and SiHa-R)." (PMID 35692795, 2022). "LDHA is a glycolysis key enzyme and regulates glycolysis rate, suggesting that lncRNA NEAT1 increases 5-FU resistance via regulation of glycolysis rate in cervical cancer cells." (PMID 36438563, 2022). "For example, a study showed that the knockdown of NEAT1 can sensitize 5-FU resistance in cervical cancer and inhibit its glycolysis via the miR-34a/LDHA axis." (PMID 36011001, 2022). "lncRNA NEAT1 was also reported to enhance cervical cancer radioresistance via miR-193b-3p/CCND1 axis." (PMID 35600868, 2022). "In cervical cancer, NEAT1 is not only related to the growth, metastasis and prognosis of cervical cancer, but also can regulate sensitivity to chemotherapy drugs." (PMID 35692795, 2022). "To investigate the roles of lncRNA-NEAT1 in cervical cancer, we initially compared the expressions of NEAT1 in 35 paired human cervical cancer tissues and their adjacent normal tissues by qRT-PCR." (PMID 33645623, 2021). "We found NEAT1 was significantly up-regulated in cervical cancer patients and cells, consistent with previous report." (PMID 33645623, 2021). "Bioinformatics analysis uncovered that NEAT1 functions as a competitive endogenous RNA (ceRNA) of miR-34a in cervical cancer cells via sponging it at multiple sites to suppress expression of miR-34a." (PMID 33645623, 2021).
cervical carcinoma (continued). "As we expected, the expressions of NEAT1 was significantly up-regulated in cervical cancer cells compared with normal cells." (PMID 33645623, 2021). "Collectively, these results demonstrated that NEAT1 facilitated the 5-Fu resistance of cervical cancer cells." (PMID 33645623, 2021). "Expectedly, co-transfection of NEAT1 shRNA and miR-34a inhibitor in cervical cancer cells showed recovered glycolysis and 5-Fu resistance, suggesting that NEAT1 suppressed miR-34a to promote the glycolysis and 5-Fu resistance in cervical cancer." (PMID 33645623, 2021). "Consistent results demonstrated exogenous overexpression of NEAT1 rendered cervical cancer cells more resistant to 5-Fu compared with control treatments." (PMID 33645623, 2021). "In accordance with our expectation, overexpression of NEAT1 effectively de-sensitized cervical cancer cells through glycolysis up-regulation." (PMID 33645623, 2021). "Concerning cervical cancer, hsa-miR-133a appears downregulated by NEAT1, which in turn results in upregulation of SOX4 and cervical cancer progression." (PMID 35008626, 2021). "Study in cervical cancer showed that high expression of NEAT1 predicted poor prognosis and promoted migration and invasion of cervical cancer cells." (PMID 33777808, 2021). "Given the aberrantly oncogenic roles of NEAT1 in cervical cancer, the effect of NEAT1 on the chemoresistance in cervical cancer cells was investigated by gain-of-function studies by transfection of NEAT1 overexpression vector in CaSki and SiHa cells." (PMID 33645623, 2021). "We detected that nuclear-rich transcripts 1 (NEAT1) was significantly up-regulated in cervical cancer tissues and cell lines." (PMID 33645623, 2021). "For instance, expression of NEAT1 is augmented in cervical cancer tissues in correlation with poor survival of patients." (PMID 33842553, 2021). "Future investigation will be devoted to determining the mechanism by which NEAT1 performs this function in cervical cancer (especially the cross-talk between NEAT1 and other tumor suppressor miRNAs or the components of polycomb repressive complex 2)." (PMID 32151082, 2020). "Collectively, we have described a previously uncharacterized role for the NEAT1/miR-361/HSP90 signaling pathway in the regulation of cervical cancer development." (PMID 32151082, 2020). "Recent mechanism experiments revealed that knockdown of NEAT1 inhibited cervical cancer development through repressing cell proliferation, migration, and invasion and also inducing cell apoptosis by regulating the miR-133a/SOX4 pathway." (PMID 32151082, 2020). "Taken together, these findings support the notion that NEAT1 promotes cervical cancer invasion and sphere formation through upregulating HSP90 expression via binding with miR-361, a tumor suppressor that directly suppresses HSP90 expression." (PMID 32151082, 2020). "We further examined the effects of NEAT1 depletion on the protein expression of HSP90 and found that the silencing of NEAT1 greatly suppressed the expression of HSP90 in cervical cancer cells." (PMID 32151082, 2020). "We have reported that the lncRNA NEAT1 functions as an oncogenic sponge for miR-361 in endometrial cancer, raising the possibility that NEAT1 potentially interacts with miR-361 and suppresses its expression in cervical cancer cells." (PMID 32151082, 2020). "The results revealed a significantly higher level of NEAT1 in cervical cancer samples compared with normal samples." (PMID 32151082, 2020). "It has been also clarified that knocking down the expression of NEAT1 in cervical cancer cells resulted in the repression of cell proliferation and invasion via the PI3K/AKT signaling pathway." (PMID 32151082, 2020). "To test this, we searched for NEAT1 expression in TCGA datasets from cervical cancer tissues and normal cervical tissues using the UALCAN database." (PMID 32151082, 2020).
cervical carcinoma (continued). "Interestingly, a recent study showed that NEAT1 downregulation led to upregulated expression of miR-34a in cervical cancer tissues." (PMID 40165339, 2025). "Thus, we believe that NEAT1 enhances migration and invasion abilities in cervical cancer cells by promoting aerobic glycolysis." (PMID 38733179, 2024). "Moreover, the RT–qPCR results indicated that the mRNA expression levels of NEAT1 in cervical cancer tissue were positively correlated with the expression of PDK1 and CTNNB1." (PMID 38733179, 2024). "In general, our findings suggested that NEAT1 functioned as an oncogene and that targeting NEAT1 could be a potential therapeutic avenue in cervical cancer." (PMID 38733179, 2024). "Glucose consumption, lactate production, ATP levels, ROS levels, MMP levels, and the mRNA expressions of glycolysis‐related genes and tricarboxylic acid cycle‐related genes were detected to analyze the effect of NEAT1 on metabolism reprograming in cervical cancer cells." (PMID 38733179, 2024). "We were then interested in whether PDK1 is the crucial factor regulating the impact of NEAT1 on aerobic glycolysis in cervical cancer cells." (PMID 38733179, 2024). "Second, although the in vitro assay clearly indicated the importance of NEAT1 in the progression and aerobic glycolysis of cervical cancer, in vivo models of cervical cancer are required for a more holistic understanding of the function of NEAT1 in cervical cancer development." (PMID 38733179, 2024). "Our results showed that NEAT1 was highly expressed in cervical cancer tissues and cell lines." (PMID 38733179, 2024). "In summary, these findings indicated that NEAT1 may contribute to the progression of cervical cancer by activating the WNT/β‐catenin/PDK1 signaling axis." (PMID 38733179, 2024). "NEAT1 was explored to stimulate cervical cancer development by blocking miR-133a expression." (PMID 37310654, 2023). "Furthermore, in 5-Fu resistant CaSki cervical cancer cells, NEAT1 expression was considerably increased." (PMID 37310654, 2023). "Knockdown of NEAT1 by siRNA reduced cervical cancer cell migration and invasion capacity." (PMID 37310654, 2023). "NEAT1 was shown to be upregulated considerably in cervical cancer tissues and cell lines." (PMID 37310654, 2023). "This may indicate that NEAT1 knockdown regulates the radiosensitivity of cervical cancer through the NEAT1/miR-193b-3p/CCND1 signalling pathway." (PMID 35692795, 2022). "Our findings suggest that targeting the NEAT1-mediated miR-34a/LDHA-glycolysis axis might be regarded as a promising therapeutic strategy against chemoresistant cervical cancer." (PMID 33645623, 2021). "In summary, we propose that the negative association between NEAT1 and miR-34a in cervical cancer cells contributes to the dysregulated cellular glycolysis, resulting in 5-Fu resistance." (PMID 33645623, 2021). "In NEAT1 knockdown cells, the cervical cancer cells showed increased 5-Fu sensitivity." (PMID 33645623, 2021). "Furthermore, expression of NEAT1 was significantly up-regulated in 5-Fu resistant CaSki cervical cancer cells." (PMID 33645623, 2021). "This negative association between NEAT1 and miR-34a was further verified in cervical cancer tissues." (PMID 33645623, 2021). "We found overexpression of NEAT1 de-sensitized cervical cancer cells to 5-Fu treatment." (PMID 33645623, 2021). "Currently, the underlying mechanisms of NEAT1 in regulating 5-Fu resistance of cervical cancer have not been elucidated." (PMID 33645623, 2021). "Importantly, such invert correlation between NEAT1 and miR-34a was further verified in cervical cancer tissues." (PMID 33645623, 2021). "Furthermore, by establishing 5-Fu resistant cervical cancer cell line, we observed obviously up-regulated NEAT1 in 5-Fu resistant cells compared with parental cells, suggesting NEAT1 is positively associated with 5-Fu resistance of cervical cancer." (PMID 33645623, 2021).
cervical carcinoma (continued). "However, the roles of the interaction of miR-34a with lncRNA NEAT1 in chemosensitivity of cervical cancer are unmasked." (PMID 33645623, 2021). "Finally, we demonstrated inhibition of NEAT1 significantly sensitized cervical cancer cells to 5-Fu through the miR-34a/LDHA pathway." (PMID 33645623, 2021). "NEAT1 regulated proliferation and invasion of cervical carcinoma by targeting Akt signaling." (PMID 32268876, 2020). "Also, NEAT1 functioned as a molecular sponge for miR-9-5p to promote the proliferation and migration of cervical cancer cells." (PMID 32151082, 2020). "Here, silencing of NEAT1 induced apoptosis in radioresistant cervical cancer cells." (PMID 32585857, 2020). "Similarly, the expression of NEAT1 was increased in cervical cancer samples compared with normal samples, and the patients expressing high NEAT1 levels showed a shorter survival time." (PMID 32151082, 2020). "To verify the direct binding relationship between NEAT1 and miR-361, we performed a luciferase reporter assay by co-transfecting cervical cancer cells with luciferase reporter plasmids containing the WT NEAT1 or the MUT NEAT1, along with miR-361 mimic or control mimic." (PMID 32151082, 2020). "We examined whether NEAT1 depletion influences miR-361 expression in cervical cancer cells using quantitative real-time PCR analysis." (PMID 32151082, 2020). "Additionally, the expression of NEAT1 was measured in cervical cancer cell lines compared with the normal cell line EM, and NEAT1 was significantly upregulated in cervical cancer cell lines." (PMID 32151082, 2020). "NEAT1 was also more abundant in radioresistant cases of cervical cancer." (PMID 32585857, 2020). "In cervical cancer NEAT1 was highly expressed in radioresistant patients." (PMID 32585857, 2020). "Also, NEAT1 was reported to promote cervical cancer development by binding and negatively modulating miR-133a expression, which belongs to the miR-133 family (including miR-133a and miR-133b)." (PMID 31344855, 2019). "Therefore, we wondered whether NEAT1 activates WNT/β‐catenin signaling pathway in cervical cancer cells." (PMID 38733179, 2024). "In addition, NEAT1 can also act as a ceRNA to inhibit the expression of miR-193b-3p, thereby upregulating the expression of cyclin D1, the downstream target of miR-193b-3p, accelerating the cell cycle and promoting the development of cervical cancer." (PMID 36890809, 2023). "By upregulating miR-193b-3 expression and downregulating CCND1 expression, NEAT1 silencing can reduce the cell survival rate and clone formation, and increase G0/G1 phase cell cycle arrest and apoptosis, thus improving the radiosensitivity of cervical cancer cells." (PMID 35692795, 2022). "Thus, NEAT1 is regarded as a pro-EMT lncRNA in cervical cancer." (PMID 33842553, 2021). "Moreover, the cellular glycolysis rates were significantly increased in 5-Fu resistant cervical cancer cells, suggesting targeting the NEAT1-mediated glycolysis could effectively overcome chemoresistance." (PMID 33645623, 2021). "However, the precise roles of lncRNA NEAT1 in 5-Fu resistance and the underlining molecular mechanisms in cervical cancer has not been elucidated." (PMID 33645623, 2021). "In addition, NEAT1 could enhance the radio-resistance of cervical cancer by suppressing miR-193b-3p-CCND1 interaction." (PMID 30053878, 2018). "Notably, the lncRNAs NEAT1 and MALAT1 have been shown to modulate radioresistance via sequestration of related miRNAs in nasopharyngeal carcinoma as well as high-risk human papillomavirus-positive cervical cancer." (PMID 28487500, 2017). "lncRNA NEAT1 knock-down was able to significantly reduce LDHA expression, lower the rate of glycolysis and sensitize the cervical cancer cells to 5-Fluorouracil." (PMID 39912983, 2025). "In this context, NEAT1 and ANRIL are markedly overexpressed in cervical cancer tissues and cell lines, correlating with more severe clinical features and reduced patient survival." (PMID 41195272, 2025).
cervical carcinoma (continued). "Mechanistically, NEAT1 upregulated pyruvate dehydrogenase kinase (PDK1) through the WNT/β‐catenin signaling pathway, which enhanced glycolysis and then facilitated cervical cancer metastasis." (PMID 38733179, 2024). "Mechanistically, NEAT1 modulated WNT/β‐catenin/PDK1 axis to facilitate aerobic glycolysis, resulting in EMT and metastasis in cervical cancer." (PMID 38733179, 2024). "LncRNA NEAT1 expression was increased during the EMT process in various diseases, such as cervical cancer, diabetic nephropathy, posterior capsule opacification, and pulmonary fibrosis." (PMID 39423195, 2024). "For example, lncRNA NEAT1 can downregulate miR-361, which can inhibit EMT process in cervical cancer cells by targeting on EMT activator HSP90." (PMID 36685972, 2022). "Suppression of lncRNA NEAT1 increased the sensitivity of 5-FU via sponging miR-34a and elevating the expression of LDHA in cervical cancer cells." (PMID 36438563, 2022). "This is because NEAT1 binds to miR-193b in a competitive manner to regulate the expression of CCND1, enhancing radioresistance in cervical cancer." (PMID 36685972, 2022). "It has been reported that Neat1 promotes tumor development by inhibiting PTEN expression in laryngeal and cervical cancer." (PMID 36335386, 2022). "Our study described a previously unappreciated connection between the NEAT1/miR-361/HSP90 axis and EMT phenotypes in cervical cancer cells." (PMID 32151082, 2020). "Here, we demonstrated that, by competitively binding to miR-361 and suppressing its expression, NEAT1 indirectly upregulates the expression of the EMT inducer HSP90, thereby promoting EMT, invasion and sphere formation of cervical cancer cells." (PMID 32151082, 2020). "In summary, our in vitro study revealed a new mechanism by which NEAT1 regulates cervical cancer progression: NEAT1 promotes aerobic glycolysis in cervical cancer cells to promote the EMT and malignant progression of cervical cancer by activating WNT/β‐catenin/PDK1 axis." (PMID 38733179, 2024). "In addition, nuclear-enriched abundant transcript 1 (Nuclear-enriched abundant transcript 1, NEAT1) is a lncRNAs highly expressed in radiation-resistant cervical cancer cells." (PMID 36890809, 2023). "that NEAT1 via targeting SRY-Box transcription factor 4 (SOX4) as a downstream target of miR-133a can induce colony formation, cell proliferation, migration, and invasion in cervical cancer cells." (PMID 37310654, 2023). "For example, NEAT1, sponging miR-9-5p, enhances the resistance of anaplastic thyroid carcinoma cells to cisplatin by regulating SPAG9 expression, promotes the growth of cervical cancer cells, and regulates pulmonary fibrosis." (PMID 35038133, 2022). "We observed a negative correlation between long noncoding RNA (lncRNA)-NEAT1 and miR-34a in cervical cancer patient tissues." (PMID 33645623, 2021). "Furthermore, we discovered that NEAT1 functions as an oncogenic lncRNA that directly suppresses miR-361 expression and induces EMT and sphere formation in cervical cancer cells." (PMID 32151082, 2020). "However, the study on the impact of NEAT1 on the EMT program and the self-renewal capacity of cervical cancer cells is limited." (PMID 32151082, 2020). "Two other lncRNAs were involved in cell cycle regulation in cervical cancer: MALAT1 and NEAT1." (PMID 32585857, 2020). "Therefore, we wondered whether the enhancing effect of NEAT1 on the expression of PDK1 and aerobic glycolysis in cervical cancer cells is mediated by the WNT/β‐catenin pathway." (PMID 38733179, 2024). "Furthermore, in cervical cancer patient tissues, there was a negative connection between NEAT1 and miR-34a." (PMID 37310654, 2023). "Importantly, knocking down NEAT1 successfully down-regulated LDHA expressions and glycolysis rate of cervical cancer cells by up-regulating miR-34a, a process could be further rescued by miR-34a inhibition." (PMID 33645623, 2021).
cervical carcinoma (continued). "Although direct targeting LDHA by miR-34a has been revealed in other cancers, in speaking of lncRNA NEAT1, its function as a ceRNA of miR-34a to further de-suppress LDHA in cervical cancer has not been elucidated." (PMID 33645623, 2021).